SLFN5 (schlafen family member 5)
Description:
May have a role in hematopoietic cell differentiation.
Synonyms: MGC19764
Tractability: PROTAC: UniProt records ubiquitination sites on it; ubiquitination databases record sites on it; its protein half-life has been measured.
Gene: Protein-coding gene on chromosome 17 (35,243,043 to 35,273,655, forward strand). Ensembl gene ENSG00000166750.
Subcellular location (Human Protein Atlas): Nucleoplasm; Vesicles
Gene Ontology:
Molecular function: ribosome binding; RNA nuclease activity
Biological process: rRNA catabolic process
Cellular component: nucleus
Genetic constraint (gnomAD): Loss-of-function variants: 34 observed, 50.99 expected, observed/expected ratio (o/e) 0.67, 90% interval 0.51 to 0.89. The upper end of that interval is the gene's LOEUF score, 0.89, which puts it in group 3 of 6, group 1 being the genes least tolerant of losing a copy. Missense variants: 1,006 observed, 1,126.6 expected, observed/expected ratio (o/e) 0.89, 90% interval 0.85 to 0.94. Synonymous variants: 387 observed, 416.32 expected, observed/expected ratio (o/e) 0.93, 90% interval 0.86 to 1.01.
Homologues: Orthologues: chimpanzee SLFN5 (97% identical), macaque SLFN5 (93% identical), guinea pig SLFN5 (67% identical), mouse Slfn5 (59% identical), rat Slfn5 (57% identical). Paralogues in human: SLFN11 (52% identical), SLFN13 (51% identical), SLFN14 (42% identical), SLFN12 (28% identical), SLFN12L (28% identical), SLFNL1 (7% identical).
Diseases named in the same sentence as SLFN5 in open-access papers:
SLFN5 is named in the same sentence as 43 diseases in open-access papers, as found by Europe PMC text mining. Sharing a sentence is not in itself a finding about the gene and the disease. The quoted sentences say what the papers report.
breast carcinoma (10 papers, 2020 to 2025). "SLFN5 is also reported to play a role in epithelial‐mesenchymal transformation in breast cancer, among others." (PMID 39891432, 2025). "Studies have shown that SLFN5, as a transcriptional repressor, is expressed in breast cancer (BRCA) and plays a role in preventing epithelial-mesenchymal transition (EMT), a key pathological process in tumor progression." (PMID 39558948, 2024). "Further studies are necessary to better elucidate the opposing roles of SLFN5 in TNBC versus other types of breast cancer." (PMID 38791884, 2024). "The context-dependent and sometimes conflicting, observations reported for SLFN5 regulatory effects, are also evident in different types of breast cancer." (PMID 38791884, 2024). "For example, SLFN5 and SLFN12 exhibit positive feedback in breast cancer, while SLFN5, SLFN11, and SLFN13 all play roles in HIV-1 regulation." (PMID 39558948, 2024). "High expression of SLFN5 in melanoma, renal cell carcinoma, and breast cancer inhibits tumor invasion and migration, indicating that SLFN5 acts as a tumor suppressor gene." (PMID 37771431, 2023). "MEG3 is downregulated in various cancers and positively correlates with SLFN5 expression in breast cancer." (PMID 37771431, 2023). "As a transcriptional repressor, SLFN5 prevents epithelial-mesenchymal transition (EMT) in breast cancer and targets the ZEB1 promoter to suppress ZEB1 transcription and downstream PTEN/AKT/cyclin D1 signaling cascade, ultimately inducing cancer cell death." (PMID 37771431, 2023). "In breast cancer, downregulation of SLFN5 protein in breast cancer cells increases ZEB1 transcriptional activity." (PMID 37771431, 2023). "We previously reported that Schlafen family member 5 (SLFN5) inhibits breast cancer malignant development by regulating epithelial-mesenchymal transition (EMT), invasion, and proliferation/apoptosis." (PMID 36033389, 2022). "On one hand, SLFN5 overexpression suppresses breast tumor growth in mice and elevated SLFN5 expression correlates with better survival in breast cancer and renal cell carcinoma." (PMID 36382088, 2022). "High SLFN5 expression in melanoma, renal cell carcinoma, and breast cancer can inhibit tumor invasion and migration, indicating that SLFN5 acts as a tumor suppressor gene." (PMID 36090985, 2022). "Herein, we demonstrated that MEG3 was downregulated in pan-cancers and correlated with SLFN5 expression positively in breast cancer by bioinformatics analysis of TCGA and UCSC Xena data." (PMID 36033389, 2022). "MEG3 repressed EMT and migration/invasion, similar to our previously reported functions of SLFN5 in breast cancer." (PMID 36033389, 2022). "SLFN5 expression has also been reported to correlate inversely with metastasis in Luminal A breast cancer." (PMID 34571887, 2021). "Taken together, in this study, we found that human endogenous and exogenous SLFN5 can maintain or restore breast cancer cells with epithelial morphology by transcriptional suppression of ZEB1 expression." (PMID 32488136, 2020). "Furthermore, the expression of MEG3 was tightly correlated with the expression of Schlafen-5 (SLFN5), and overexpression of MEG3 ameliorated EMT in highly invasive breast cancer cells by modulating SLFN5 expression via MEG3/miR-146b-5p/SLFN5 axis." (PMID 40176927, 2024). "Regarding breast cancer patients with aggressive disease and poor tolerance to chemotherapy, assessing and increasing the expression of SLFN5 may be essential." (PMID 39558948, 2024). "Therefore, we conclude that MEG3 positively modulates SLFN5 expression by sponging miR-146b-5p and inhibits breast cancer development." (PMID 36033389, 2022). "Intervention with MEG3 positively affected SLFN5 expression in breast cancer cells." (PMID 36033389, 2022). "However, work from the Lu group on the role of SLFN5 in breast cancer cells shows that SLFN5 could be considered a tumor suppressor in the context of TNBC by inhibiting the aggressiveness commonly seen by TNBC." (PMID 38791884, 2024).
breast carcinoma (continued). "SLFN5 is expressed in estrogen receptor (ER)-positive breast cancer cells, while triple-negative breast cancer (TNBC) cells lack SLFN5 or exhibit very low levels." (PMID 38791884, 2024). "Human SLFN5, SLFN11, SLFN12, SLFN13, and SLFN14 are all downregulated in breast cancer, lung squamous carcinoma, prostate cancer, and rectal carcinoma." (PMID 34571887, 2021). "To investigate the role of SLFN5 in BRCA, we first downloaded the processed TCGA breast cancer FPKM gene expression matrix and the clinical information for all 840 BRCA patients and 113 normal individuals." (PMID 32488136, 2020).
glioblastoma (7 papers, 2020 to 2024). The most malignant astrocytic tumor (WHO grade IV). "Decreasing SLFN5 leads to increased cellular susceptibility to IFN-induced antiproliferative responses in glioblastoma cells, implying that SLFN5 functions as a negative regulator of the IFN response in glioma cancer cells." (PMID 35216035, 2022). "Targeting SLFN5 may serve as a promising approach for the treatment of drug-resistant glioblastoma and/or the elimination of glioma cancer stem cells, but further research is needed to explore its feasibility and effectiveness." (PMID 37771431, 2023). "However, elevated SLFN5 expression in glioblastoma, pancreatic ductal adenocarcinoma, and prostate cancer promotes tumor proliferation, invasion, and metastasis." (PMID 37771431, 2023). "A glioblastoma study identified SLFN5 as a regulator of STAT1 induction by type I IFNs." (PMID 33329603, 2020). "In glioblastoma multiforme (GBM), high levels of all human Schlafens (SLFN5, SLFN11, SLFN12, and SLFN13) are correlated with shorter overall survival of patients." (PMID 34571887, 2021). "SLFN5 also negatively controls STAT1-mediated transcriptional activation of IFN-stimulated genes and ZEB1 transcription, suppressing the antitumor immune response in glioblastoma cells and the mesenchymal-epithelial transition." (PMID 35768579, 2022). "Work by other authors has reported an SLFN5 co-repressor action with STAT1 in IFN-mediated responses, by promoting malignant progression in glioblastoma, but a direct transcriptional role has not been yet reported." (PMID 32488136, 2020). "Firstly, downregulation of SLFN5 promotes the formation of soft agar colonies/non-anchorage-dependent growth in human melanoma cells, but does not affect the proliferation of renal cell carcinoma (RCC) cells, and even enhances the growth of glioblastoma cells." (PMID 37771431, 2023).
melanoma (7 papers, 2020 to 2024). A malignant, usually aggressive tumor composed of atypical, neoplastic melanocytes. "In that context, our group has previously demonstrated the importance of SLFN5 expression for the antitumor effects of IFNα in malignant melanoma cells." (PMID 38791884, 2024). "On the other hand, in malignant melanoma cells, SLFN5 appears to play a different role, suppressing anchorage-independent growth and invasion of cancerous melanoma cells." (PMID 38791884, 2024). "Due to the dependency of SLFN5 protein on I-type interferon (IFN), it is well-established that SLFN5 plays a critical role in the inhibitory effects of IFNα on the growth and invasion of malignant melanoma cells." (PMID 37771431, 2023). "The induction of human SLFN5 by human IFNα in malignant melanoma cells suggests its specific involvement in the IFNα response pathway." (PMID 37771431, 2023). "In contrast, the depletion of SLFN5 boosted the ability of melanomas to form colonies, even in the presence of IFN." (PMID 35216035, 2022). "In mouse malignant melanoma and renal cell carcinoma, IFNα promotes the expression of Slfn1, Slfn2, Slfn3, Slfn5, and Slfn8." (PMID 35216035, 2022). "All human Schlafen mRNA expression was induced in normal melanocytes by IFN therapy, while only SLFN5 was induced in malignant melanoma cells and renal cell carcinoma cells." (PMID 35216035, 2022). "This suggests a specific role of SLFN5 in the pathogenesis of melanomas and the importance of SLFN5 downregulation in promoting melanoma tumorigenesis." (PMID 34571887, 2021). "Interferon (IFNα) induces the expression of Slfn1, Slfn2, Slfn3, Slfn4, Slfn5, and Slfn8 in B16-F1 malignant murine melanoma cells and murine renal cell carcinoma cells (RCC)." (PMID 34571887, 2021). "Although SLFN11, SLFN12, SLFN13, and SLFN14 are expressed comparably in primary melanocytes and malignant melanoma cells, the high expression of SLFN5 in primary melanocytes is suppressed at both mRNA and protein levels in malignant melanoma cells." (PMID 34571887, 2021). "Slfn5, Slfn8, Slfn9, and Slfn10 are all upregulated in melanoma cells upon treatment with IFN-α and in splenocytes after infection with Listeria monocytogenes." (PMID 34571887, 2021). "Enhancing the inhibitory effects of SLFN5 expression in malignant melanoma cells may confer a growth advantage and promote tumor development." (PMID 37771431, 2023). "For example, SLFN5 expression is suppressed in malignant melanoma compared to normal melanocytes." (PMID 35216035, 2022). "Interestingly, IFN-I substantially upregulates SLFN5 in malignant melanoma cells, in normal renal proximal tubule epithelial cells (RPTEC), and human renal adenocarcinoma cells (786-O and ACHN RCC cells), with minimal or no induction of other human Schlafens." (PMID 34571887, 2021). "Additionally, collagen invasion plays a crucial role in melanoma progression, and the knockdown of SLFN5 also results in augmented invasion of three-dimensional collagen, indicating that SLFN5 has a dual role in regulating the invasion and anchorage-independent growth of melanoma cells." (PMID 37771431, 2023). "For instance, type I IFNs induced the expression of SLFN5, SLFN11, SLFN12, and SLFN13 in normal melanocytes, but in melanoma cell lines, only SLFN5 was inducible." (PMID 38791884, 2024). "When melanoma cells are stimulated with IFN, SLFN5 expression is considerably increased, decreasing cancer cell proliferation." (PMID 35216035, 2022). "Knockdown of Slfn2 or Slfn3, but not Slfn5, increases proliferation and anchorage-independent growth in murine melanoma cells." (PMID 34571887, 2021). "Knockdown of Slfn2 or Slfn3, but not Slfn5, increases cell proliferation and anchorage-independent growth and reduces the antiproliferative effect of interferon in murine melanoma cells." (PMID 34571887, 2021).
melanoma (continued). "However, SLFN5 also potentially reduces the anticancer effect of IFN in glioma cancer cells by transcriptionally co-repressing STAT1-mediated IFN responses, in contrast to its beneficial role in melanoma and renal cell carcinoma." (PMID 35216035, 2022). "In these cells, IFN-α2 treatment induced expression of SLFN5 but no other SLFNs, suggesting a distinct role for SLFN5 in IFN responses in melanoma." (PMID 38791884, 2024). "In melanoma cells, IFN-α2 is able to induce only human SLFN5 gene expression, while other SLFN family members were not induced." (PMID 38067362, 2023). "Unlike the observations in malignant melanoma and RCC, SLFN5 inhibits the anti-tumor effect of interferon in glioma multiforme cells by binding and co-repressing STAT1 stimulation." (PMID 34571887, 2021).
renal cell carcinoma (6 papers, 2021 to 2023). "In renal cell carcinoma, SLFN5 is also associated with clinical prognosis." (PMID 37771431, 2023). "SLFN5 inhibits the motility and invasiveness of malignant renal cell carcinoma cells by negatively controlling the expression of matrix metalloproteinase genes (such as MMP-1 and MMP-13)." (PMID 37771431, 2023). "Higher SLFN5 expression correlates with better overall survival of patients with renal cell carcinoma." (PMID 34571887, 2021). "In vitro overexpression of SLFN5 reduces the motility and invasiveness of malignant human renal cell carcinoma (RCC) cells by negatively regulating the expression of MMP-1 and MMP-13." (PMID 34571887, 2021). "Therefore, SLFN5 has the potential to serve as a novel clinical indicator for the prognosis of renal cell carcinoma (RCC)." (PMID 37771431, 2023). "However, reducing Slfn5 in mouse renal cell carcinoma cells increases cell proliferation and anchorage-independent growth, and reduces the antiproliferative effect of interferon." (PMID 34571887, 2021).
viral infection (6 papers, 2022 to 2026). "In light of these findings, our comprehensive analysis supports the involvement of SLFN5 in viral infections (IAV and SARS-CoV-2) and underscores its genetic regulation mediated by altering chromatin accessibilities." (PMID 40759647, 2025). "We found that SLFN5 expression was significantly reduced in A549 cells exposed to heat-inactivated HIV-1 when compared to cells infected with replication-competent virus, indicating that active viral infection is required to induce SLFN5 expression." (PMID 41405390, 2026). "Additionally, BNIP3L was elevated in bacterial infection, potentially reflecting its role in mitophagy, while DNMT1, IFI27, SLFN5, and AHNAK were elevated in viral infection, and PABPC4 was elevated in KD." (PMID 39240972, 2024). "Additionally, Slfn5, with shared DRE sites between IBP and viral infections, inhibited apoptosis by regulating the mTOR pathway." (PMID 37081881, 2023). "Another DNA virus, adenovirus, was unaffected by SLFN5, and viral infection did not result in SLFN5 protein degradation." (PMID 35216035, 2022).
gastric cancer (5 papers, 2021 to 2024). A primary or metastatic malignant neoplasm involving the stomach. "In gastric cancer (GC) cells, SLFN5 has been associated with the aggressive transition from intestinal metaplasia to GC83." (PMID 35768579, 2022). "Thus, elevated SLFN5 protein expression in IM subjects was associated with gastric cancer progression." (PMID 37771431, 2023). "Comparative analysis using the TCGA database demonstrated significantly higher expression of SLFN5 in gastric tumor tissues compared to normal tissues, suggesting that SLFN5 may promote the development of gastric cancer." (PMID 37771431, 2023). "Additionally, SLFN5 was shown to co-localize in conjunction with T cells and type 2 macrophages in precancerous stomach lesions, indicating an immunosuppressive function of SLFN5 in gastric cancer." (PMID 39558948, 2024). "Previous studies have found that the increased SLFN5 expression in patients with intestinal metaplasia correlates with gastric cancer (GC) progression." (PMID 36090985, 2022). "Therefore, as in gastric cancer, SLFN5 expression is an unfavorable prognostic predictor for CRPC." (PMID 34571887, 2021). "Currently, there is limited research on the role of SLFN5 in gastric cancer (GC)." (PMID 37771431, 2023). "In contrast to the apparent adverse roles of SLFN5 and SLFN12L in gastric cancer, analysis of gastric carcinomas from 169 patients suggested that high SLFN11 expression correlates with better survival, which improves when patients are treated with platinum-chemotherapy." (PMID 34571887, 2021). "Therefore, SLFN5 and SLFN12L gastric stromal expression could serve as a potential predictor of intestinal metaplasia progression to gastric carcinoma." (PMID 34571887, 2021). "Although normal human gastric mucosa has been reported to express minimal or no SLFN5 protein, SLFN5 expression is upregulated in patients with atrophic gastritis, both intestinal and diffuse subtypes of gastric carcinoma, and in intestinal metaplasia that has progressed to gastric cancer." (PMID 34571887, 2021).
glioma (4 papers, 2020 to 2024). A benign or malignant brain and spinal cord tumor that arises from glial cells (astrocytes, oligodendrocytes, ependymal cells). "Knockdown of SLFN5 enhances cellular sensitivity to IFN-induced antiproliferative responses in glioma stem-like cancer cells, making SLFN5 a negative regulator of the IFN-response in glioma cancer cells." (PMID 34571887, 2021). "Specifically, the expression levels of SLFN5, SLFN11, and SLFN12 are positively correlated with glioma grade, highest in the more aggressive grade IV compared to grade I, II, or III tumors." (PMID 34571887, 2021).
lung carcinoma (4 papers, 2020 to 2023). "Regarding signaling pathways, human SLFN5 exerts inhibitory effects on lung cancer progression through the PTEN/PI3K/AKT/mTOR pathway." (PMID 37771431, 2023). "SLFN5 expression has been reported to be prognostically favorable in lung cancers, but it activates epithelial to mesenchymal transition in vitro." (PMID 32987632, 2020). "Collectively, the data strongly suggest that SLFN5 may play a crucial role in improving the prognosis of lung cancer patients and has the potential to serve as a valuable biomarker for predicting patient outcomes." (PMID 37771431, 2023). "The results unveiled that SLFN5 overexpression promotes EMT in lung cancer cells." (PMID 37771431, 2023). "SLFN5 expression is highly correlated with the clinicopathological characteristics of NSCLC (TNM classification), suggesting that SLFN5 may contribute to tumorigenesis and progression of lung cancer." (PMID 34571887, 2021). "High expression of either SLFN5 or SLFN11 has been reported to be prognostically favorable for lung cancer, and SLFN11 in particular has also been reported to sensitize lung cancer cells to DNA alkylating agents and poly ADP ribose polymerase (PARP) inhibitors." (PMID 32987632, 2020). "In recent years, emerging genes have been revealed to be the potential therapeutic targets of lung cancer by inhibiting the PI3K/AKT/mTOR pathway, such as SREBP, DOK7V1, HRH3, SLFN5, and FABP5." (PMID 36349192, 2022).